MMP2 (matrix metallopeptidase 2)
Diseases named in the same sentence as MMP2 in open-access papers (continued):
Sharing a sentence is not in itself a finding about the gene and the disease.
breast cancer (continued). "In this study, immunohistochemical analysis of Twist, MMP-2 and MMP-9 expression was performed on tissue microarrays from 200 breast cancer cases." (PMID 23935727, 2013). "We show here that AngII up-regulates MMP2 and MMP9 gene expression and enzymatic activity in breast cancer cells, in agreement with studies conducted in the gastric cancer cell line MNK-28." (PMID 22536420, 2012). "The mRNA expression levels of MMP-2 were significantly elevated (p < 0.05) in the MDA-MB-435 and in the Hs578T (p < 0.001) breast cancer cell lines relative to MCF-7 cells." (PMID 22260435, 2012). "For this reason, we first analyzed the mRNA expression levels of MMP-2, MMP-9, MMP-14, TIMP-1, TIMP-2, TIMP-3 and RECK, in the same panel of five human breast cancer cell lines, but now maintained in culture until achieving 80-90% confluence." (PMID 22260435, 2012). "Taken together, the results obtained demonstrate that TGF-β1 is a common regulator of MMPs (MMP-2 and MMP-9) and their inhibitors (TIMP-2 and RECK) in breast cancer cell models." (PMID 22260435, 2012). "Kim and collaborators suggested that TGF-β1 also induces invasion in pre-malignant breast cancer cells (MCF10A), by upregulation of MMP-2 and MMP-9." (PMID 22260435, 2012). "The activities of both the pro- and activated forms of MMP-2 and MMP-9 were measured by gelatin-zymography of the plasma of fourteen dogs with mammary tumors and three healthy control dogs." (PMID 21726449, 2011). "In conclusion, we have evaluated the involvement of MMP-2, MT1-MMP, MMP-9 and various TIMPs in canine mammary tumors, with an emphasis on the stromal compartment." (PMID 21726449, 2011). "Stimulation of the B2R induces MMP overexpression and cell migration in a rat astroglial cell line, while the B1R induces release of MMP-2 and MMP-9 in breast cancer cells." (PMID 21729302, 2011). "On the other hand, B1R stimulation induces release of MMP-2 and MMP-9 via an ERK-dependent pathway in estrogen-sensitive and-insensitive breast cancer cells." (PMID 21729302, 2011). "In this study, the mRNA and protein levels of MMP-2, MMP-9, MMP-13, MT1-MMP and TIMP-2 in benign and malignant mammary tumors were thoroughly analyzed." (PMID 21726449, 2011). "Added at 10 pg ml–1 to the MDA-MB-231 breast cancer cells, PGE2 has increased cancer cell invasion and the release of MMP-2." (PMID 21792195, 2011). "Both MMP-2 and MT1-MMP have previously been detected by immunohistochemistry in canine mammary carcinomas." (PMID 21726449, 2011). "This study provides evidence that inactivation of PI3K/Akt signaling pathway by ANT2 shRNA down-regulates MT1-MMP, MMP2, and MMP9 expression and activity as well as VEGF expression in a HER2/neu-overexpressing breast cancer cell line." (PMID 20650008, 2010). "Our results demonstrated that melatonin, via its MT1 receptor, plays an inhibitory role in breast cancer cell invasion, possibly by specifically downregulating the p38 MAPK signaling pathway, and the downstream activity of MMP-2 and MMP-9." (PMID 21167057, 2010). "Our results demonstrated that melatonin suppresses the in vitro invasive potential of breast cancer cells by altering the phosphorylation of p38 MAPK and the downstream activity of MMP-2 and MMP-9." (PMID 21167057, 2010). "The expression of the two gelatinases, MMP-2 and MMP-9, in breast cancer is well investigated in many studies using different methods." (PMID 19531263, 2009). "We studied the effect of ATRA on MMP-2 in MCF-7, human breast cancer cells, and the probable signaling pathways which are affected by ATRA on regulating pro-MMP-2 activity and expression." (PMID 19636436, 2009). "Elevated expression of MMP-2 and MMP-9 is positively correlated with HER-2 overexpression in mammary tumors." (PMID 20169097, 2009). "The tissue levels of at least MMP-1, MMP-2, MMP-9, MMP-11, membrane type (MT) 1-MMP, tissue inhibitors of metalloproteinases (TIMP) 1 and TIMP-2 have been correlated with poor outcome of breast cancer patients." (PMID 19243594, 2009).
breast cancer (continued). "There is precedence for the role of IGF-1 in this regard via its effects on MMPs, such as MMP-2 and MMP-9 in MCF-7 breast cancer cells and in androgen-independent PC3 prostate cancer cells." (PMID 18598360, 2008). "Previous studies have examined the value of biomarkers such as carcinoembryonic antigen, CA 15-3, MMP-2, MMP-9, tissue polypeptide antigen (TPA), tissue polypeptide-specific antigen (TPS), EGFR, and HER-2/neu in predicting response to NAC for breast cancer." (PMID 18474099, 2008). "Not surprisingly, experimental evidence supports a critical role of MMPs, such as MMP-2 and MMP-9, in the invasion and metastasis of breast cancer." (PMID 18373849, 2008). "In fact, both MMP-2 and MMP-9 have been extensively studied as biomakers and as well as therapeutic targets in breast cancer." (PMID 18373849, 2008). "To further address a possible role for MMPs in IL-17-dependent invasiveness of breast cancer cell lines, we assayed the supernatants from IL-17-treated and control MDA-MB231 and MDA-MB453 cells for the presence of MMP-2, MMP-3, MMP-9 and TIMP-1." (PMID 19014637, 2008). "Monocyte MMP-2 enzymatic activity and MMP-2 as well as TIMP-1 and TIMP-2 protein levels were increased in response to soluble factors from MCF-7 and MDA-MB-231 breast cancer cells." (PMID 16168111, 2005). "The densitometric measures of MMP-2 and MMP-9 activity levels indicated that the average values of both gelatinase activities were significantly higher in breast cancers than in control sera (P<0.0001)." (PMID 15054465, 2004). "The statistical analyses have shown a significant increase of activity levels of both MMP-2 and MMP-9 in the sera of breast cancer patients compared with control sera." (PMID 15054465, 2004). "Yavelow and co-workers have shown that AAT inhibits human breast cancer cells MCF-7 growth and AAT was also shown to block the activation of pro MMP-2 and tumor cell invasion." (PMID 15555067, 2004). "Triterpenes have also decreased matrix metalloproteinases (MMP) in rodents, especially MMP-2 and -9, which seem to play a crucial role in breast cancer tumorigenesis, though their role is not completely understood." (PMID 41322296, 2025). "Furthermore, E2-ERα signaling drives MMP-2, MMP-9, and MT1-MMP upregulation, promoting ECM remodeling and thereby enhancing breast cancer cell invasion and migration, while ERβ has also been found to regulate the expression of MMP-2 and MMP-7." (PMID 41228316, 2025). "Not all breast cancer cells express MMP-2; those which do are able to pass through the basement membrane and the extracellular matrix and enter the circulation." (PMID 41373503, 2025). "MMP2 (gelatinase A) and MMP9 (gelatinase B) are members of the MMPs family that have been shown to play a functional role in tumor angiogenesis, invasion, and metastasis, as well as in the carcinogenesis of breast cancer." (PMID 40735254, 2025). "Liposomes incorporating this conjugate (S-Peps-PEG5K) were formulated to evaluate whether MMP-2-mediated peptide degradation triggers detachment of long-chain PEG moieties, thereby enhancing internalization by 4T1 breast cancer cells." (PMID 40732329, 2025). "Additionally, Ethyl gallate has been demonstrated to downregulate the mRNA expression of MMP-2 and MMP-9 of mammary cancer cells, thereby inhibiting cell invasion and proliferation." (PMID 40166460, 2025). "Furthermore, in addition to impacting endothelial cells and curtailing the production of matrix metalloproteinase-2 (MMP-2), methylated selenium has also been shown to inhibit vascular endothelial growth factor (VEGF) expression in breast cancer cells." (PMID 39839762, 2024). "Moreover, LOX, MMP-2, and MMP-9 are more highly expressed in breast cancer tissues with axillary lymph node metastasis, suggesting a potential synergistic role in breast cancer metastasis." (PMID 39247609, 2024). "In particular, the activation of MMP-2 and MMP-9 could enhance the potential for tumor cell metastasis in breast cancer." (PMID 38794187, 2024).
breast cancer (continued). "Consistently, Q decreased the protein levels of MMP-2 and MMP-9 in breast cancer cell lines." (PMID 39474040, 2024). "A high expression of MMP-2 and MMP-9 was found in breast cancer patients." (PMID 39132498, 2024). "For this reason, we decided to evaluate whether Brazilin influence the expression of EMT markers such as E-cadherin, vimentin, and Twist, the secretion levels of MMP-2 and MMP-9 and the invasion of MCF7 and MDA-MB-231 breast cancer cells." (PMID 38737746, 2024). "The aim of this study was to evaluate the antioxidant activity of four different dietary polyphenolic compounds and their ability to inhibit ROS production in THP-1 macrophages and the activity of MMP-2 and MMP-9 in both THP-1 macrophages and in sera from patients with breast cancer." (PMID 38675538, 2024). "Also, Balakrishnan and co-workers reported the inhibition of MMP-2 and MMP-9 protein expression in MCF-7 and MDA-MB-231 breast carcinoma cells after quercetin treatment." (PMID 39335164, 2024). "Similarly, FOXM1 regulates cell migration and invasion via MMP-2 and MMP-9 in tumors such as glioblastoma, colorectal carcinoma, and breast carcinoma." (PMID 39594778, 2024). "CXCL1 induces breast cancer cell migration through the activation of extracellular signal-regulated kinase (ERK) MAPK, which increases the expression of matrix metalloproteinase 2 (MMP2) and matrix metalloproteinase 9 (MMP9)." (PMID 37108425, 2023). "Several studies suggest that ATF2 may function as an oncogene, worsening the outcome of the disease, as it increases the transcription of genes such as MMP2, MMP13, cyclin A, and aromatase that contribute to the progression and metastasis of breast cancer." (PMID 37955015, 2023). "Further studies may be undertaken to complement these histological findings via qPCR by investigating the expression of MMP-2 and other relevant MMPs such as MMP-14 in whole mammary tumours." (PMID 37297024, 2023). "Although MMP-9 transcription in MCF-7 breast cancer cells was not sensitive to E2 or ethanol, MMP-2 transcription was stimulated by these compounds." (PMID 36310188, 2023). "By suppressing mRNA expression levels of Bcl-2, cyclin D1, Bcl-xL, MMP-2, and vascular endothelial growth factor (VEGF) in MDA-MB-231 and MCF-7 breast cancer cells, DATS intervention significantly reduced leptin-induced cell proliferation, clonogenic cell viability, invasion and migration potential." (PMID 37021043, 2023). "Chronic stress-induced activation of β2-adrenoceptor results in elevated cAMP and increased intracellular calcium that enhance expression of vascular endothelial growth factor (VEGF), matrix metalloproteinase 2 (MMP2) and MMP9, hereby enhancing the invasiveness of breast cancer cells." (PMID 37773152, 2023). "There was an inverse correlation between the expression of MMP-2 and MMP-9 in breast cancer." (PMID 37798646, 2023). "Apple polyphenol extracts inhibited the proliferation and migration of human breast cancer MDA‐MB‐231 cells by reducing the expression of ubiquitin like with PHD and ring finger domains 1 (UHRF1), matrix metalloproteinase 2 (MMP2), DNA methyltransferase 3 alpha (DNMT3a), and DNMT3b." (PMID 37701204, 2023). "MMP-2, a member of the MMP family, is highly expressed in breast cancer." (PMID 37514054, 2023). "Numerous studies have examined an association between MMP-2, MMP-9, and MMP-11 expression and clinicopathological characteristics of breast cancer (BC); however, no research has been done on the MMP expression levels in BC cases from Ethiopia." (PMID 37798646, 2023). "CUR was reported to regulate the metastasis of breast cancer cells via inhibiting MMP-9 and MMP-2." (PMID 36003508, 2022). "Interestingly, the expression of MMP-2 and MMP-9 is upregulated in breast cancer, and their expression level is correlated with lymph node metastasis and tumor staging." (PMID 35847867, 2022).
breast cancer (continued). "Moreover, it was found that migration and invasion of breast cancer cells induced by BMP also correlate with increased expression of metalloproteinases, namely MMP-2, MMP-9 and MMP-14." (PMID 36139691, 2022). "Furthermore, the treatment of MCF-7 human breast cancer cells with ATRA, resulted in substantial inhibition of the expression and activity of the pro-MMP2 enzyme as well as a significant induction in TIMP2 protein expression." (PMID 36135009, 2022). "HSYA can inhibit the metastasis-related protein matrix metalloproteinase 2 (MMP2) in MDA-MB-231 cells to inhibit the migration and invasion of breast cancer cells and can promote apoptosis of breast cancer cells by activating the caspase-3-dependent apoptosis pathway." (PMID 35795285, 2022). "The level of MMP2 protein decreased and the level of E-cadherin protein increased, which verified that the metastasis ability of glioblastoma cells was inhibited, which is consistent with the regulatory mechanism involved in TRAF4 in breast cancer." (PMID 36077559, 2022). "When MDA-MB-231 breast cancer cells were detached from ECM, the epithelial to mesenchymal transition (EMT) response was induced and several EMT genes were upregulated, such as integrin αv, TGF-β1, Snail, Slug, and MMP-2." (PMID 35628507, 2022). "It was observed that NOTCH-1 activation is responsible for inducing the MMP-2 and MMP-9 expression and stimulation while lowering the regulation of NOTCH-1 involved in lowering the MMP-2 and MMP-9 activation to hinder cell progression in breast cancer and pancreatic cancer cells." (PMID 36359888, 2022). "The αvβ3 integrin activates MMP-2- and MMP-9-dependent pathways in breast cancer metastasis." (PMID 35163668, 2022). "Besides, another study established that leptin elevates the expression levels of Twist and β-catenin, as well as the release of invasion markers MMP-2 and MMP-9 in breast cancer cells, leading to enhanced cell invasion in an SRC- and FAK-dependent way." (PMID 35379785, 2022). "The expression level of MMP2 and MMP9 was closely involved in breast-cancer metastasis." (PMID 36497431, 2022). "More specifically, it was then also shown that treatment with the monoclonal antibody 4C5 blocked zymogens MMP2 and MMP9 processing to their active forms which concurred with disruption of their interactions with eHsp90 and inhibition of breast cancer cell metastasis to the lung." (PMID 36060252, 2022). "In contrast, in MDA-MB-231 breast cancer cells, it was demonstrated that PIMT was stimulated by a co-treatment with TGF-β1/TNF-α, which also increased mRNA levels of EMT markers including those of Snail, Slug, MMP-2, MMP-9, and Fibronectin." (PMID 35628507, 2022). "However, LOX silencing in breast cancer cells by siRNA can downregulate the expression of matrix metalloproteinase 2 (MMP-2) and MMP-9 in breast cancer tissues." (PMID 36293126, 2022). "Moreover, current studies have shown that DCH can reduce the activity levels of MMPs, particularly MMP2 and MMP9, in breast cancer, glioma, and oral squamous cell carcinoma." (PMID 36408277, 2022). "GH/GHR could mediate the TME and signal transduction including JAK/STAT, MAPK/phosphatidyl inositol 3 kinase (PI3K)/Akt, matrix metallopeptidase 2, and VEGF/VEHGR in gastric cancer, breast cancer, and melanoma." (PMID 36016614, 2022). "As MMP-2 can be secreted by cancer cells, murine breast carcinoma 4T1 cells were chosen as MMP-2-positive cancer cells due to the high level of MMP-2 expression, whereas 3T3 cells were taken as a negative control." (PMID 36451698, 2022). "Furthermore, calycosin treatment significantly reduced the levels of CD147, MMP-2, and MMP-9 in TGFβ1-overexpressing breast cancer cells." (PMID 34096887, 2021). "In Pellikainen JM’s report, the high MMP-2 expression in cancer cells had no prognostic value for breast cancer patients." (PMID 34027107, 2021).
breast cancer (continued). "Through gain and loss of function and rescue experiments, we confirm that MIR200CHG regulates the expression of tumor-associated proteins CDKN2A, cyclin D1, cyclin E1, BCL2, BAX, MMP1, MMP2, and MRP1 by binding YB-1, thereby promoting breast cancer proliferation, invasion, and resistance." (PMID 34272387, 2021). "DACH1 could decrease the expression of MMP9 and MMP2 in in gastric cancer, so the effect of DACH1 on the expression of MMP9 and MMP2 was examined in breast cancer cells." (PMID 34772908, 2021). "The expression of MMP2 and MMP14 in human breast cancer samples was detected using IHC, and the results showed that GABARAP negatively correlated with MMP2 and MMP14, which indicates that GABARAP also inhibits invasion and metastasis in human breast cancer samples." (PMID 33591943, 2021). "MMP-2 and MMP-9 are also involved in each stage of breast-cancer-to-bone metastasis." (PMID 34445715, 2021). "The levels of CD147, MMP-2 and MMP-9 transcripts and proteins were significantly increased in BATF-overexpressing breast cancer cells and significantly reduced in BATF-silenced breast cancer cells." (PMID 34096887, 2021). "Finally, we conducted Western Blot, and the results suggested that in MDA-MB-231 cells, C5AR2 overexpression led to the obviously upregulated levels of MMP2 and MMP9, indicating that C5AR2 was related to EMT in breast cancer." (PMID 34595119, 2021). "Among these proteins, MMP-2 and MMP-9 showed the highest correlation with SCUBE3, suggesting that they may be functional partners in breast cancer." (PMID 34006286, 2021). "Overexpression of SCARA5 downregulated MMP-2, MMP-3 and MMP-9 in breast cancer cell." (PMID 33758617, 2021). "Calycosin significantly increased the expression of E-cadherin (epithelial cell biomarker) and decreased the expression levels N-cadherin and Vimentin (mesenchymal cell biomarkers) as well as CD147, MMP-2, and MMP-9 (pro-metastatic proteins) in the breast cancer cells." (PMID 34096887, 2021). "They found that exosomes isolated from macrophages after coculture with apoptotic breast cancer cells demonstrated the ability to induce proliferation, invasiveness, and metastasis of breast cancer in vitro and in vivo by activating STAT3 and its target genes CyclinD1, MMP2, and MMP9." (PMID 34207035, 2021). "Mainly, MMP-2 and MMP-9 are most well-studied in cancer cells since these MMPs are highly secreted in breast cancer cells as a proenzyme before activation through hydrolysis and degrade collagen type-IV basement membrane (BM), which in turns alters the ability of BM to disrupt cancer cell mobility." (PMID 34181339, 2021). "Inhibition of MMP2 and MMP9 produces anti-metastatic effects in breast cancer and HCC." (PMID 35011007, 2021). "In MCF-7 (ER-positive) breast cancer cell lines, upregulation of MMP-2 significantly correlated with invasiveness, and metastatic human breast cancer tumors showed higher levels of MMP-2 than non-metastatic tumor tissue." (PMID 34944905, 2021). "TAK-242, a specific inhibitor of TLR4, was reported to considerably attenuate epithelial–mesenchymal transition (EMT) in ovarian and breast cancer cells by suppressing extracellular degradation through targeting TLR4 and regulating matrix metalloproteinase-2 (MMP-2) and MMP-9 expression." (PMID 33576897, 2021). "Moreover, MMP2 was reported to be over-expressed in several solid tumors, including CRC, gastric carcinoma, breast carcinoma, lung cancer, etc." (PMID 34976953, 2021). "Finally, MMP2 was reported to be over-expression in several solid tumors, including CRC, gastric carcinoma, breast carcinoma, and lung cancer, etc." (PMID 34976953, 2021). "It is possible that the involvement of MMP-2 and -9 in XCL1-induced breast cancer cell migration may be dependent on cell type." (PMID 33374849, 2020).